MTOR (mechanistic target of rapamycin kinase)
Diseases named in the same sentence as MTOR in open-access papers (continued):
Sharing a sentence is not in itself a finding about the gene and the disease.
tumor (continued). "RAF/MEK/mTOR inhibitors were among the top-ranked hits with suggested positive treatment effects on HR + BC of the young—being in line with our finding of gene expression patterns reflecting increased oncogenic signalling in tumours of the young." (PMID 35995935, 2022). "We investigated whether YTHDF2 overexpression activates key signaling pathways in LUSC cells, such as the ERK/MAPK and mTOR/AKT signaling pathways known to play a role in tumor proliferation and survival." (PMID 34996459, 2022). "Due to the difficult predictability of response to mTOR inhibitors and missing general predictors, tumor tissue editing could provide a prerequisite to enhance efficacy of mTOR inhibitors." (PMID 35814409, 2022). "Moreover, tumours with a high number of mitoses were less likely to have a high p-mTOR intensity score." (PMID 35883491, 2022). "The PI3K/AKT/mTOR pathway promotes neoplasm proliferation and survival by repressing autophagy." (PMID 35485300, 2022). "A recent report has found that fasting could induce the upregulation of FDFT1, a tumor suppressor gene to attenuate the AKT/mTOR/HIF pathway, thus inhibiting tumor glycolysis and proliferation in a CRC mouse model." (PMID 36319992, 2022). "Moreover, blockages of ATM, MAPK, and mTOR signaling with respective inhibitors prevented citrate‐induced upregulation of ACLY in tumor cells." (PMID 34747157, 2022). "However, as collateral damage, mTOR blocks autophagy and thereby simultaneously sensitizes such cisplatin- or PI3Ki-resistant tumor cells to drugs that interfere with glycolysis, i.e., the Warburg effect." (PMID 35681458, 2022). "Furthermore, combination treatments with bevacizumab plus FO/Se have been shown to significantly inhibit tumor PI3K/Akt/mTOR and Ras/Raf/MEK/ERK signaling, and anti-apoptotic proteins in a dose-dependent manner by FO/Se in TNBC tumor-bearing mice." (PMID 36483592, 2022). "We show that the Akt/mTOR pathway mediates downstream signaling to influence tumor progression in Aur A/B inhibited cells and this suggests opportunities for combination strategies to address cells that may bypass aurora Kinase inhibition." (PMID 35332150, 2022). "Furthermore, KRT17 knockout can also inhibit tumour cell proliferation, migration and invasion through the mTOR/S6K1 signaling pathway." (PMID 35281081, 2022). "In this regard, targeting the Akt1/mTOR/DNA-PK signaling axis could be critical for limiting ERMS tumor regrowth and recurrence." (PMID 36139434, 2022). "These GSlo tumor cell populations were high for p-4EBP1 yet low for p-mTOR S2448." (PMID 36256480, 2022). "This phenotype depended on mTOR activity, suggesting a role for mTOR in modulating cellular glucose metabolism which may translate to tumor cells, likely with a varying impact on cell division in different tumor types." (PMID 35244142, 2022). "SMYD3 interaction with AMPK and mTOR may allow tumor cells to overcome the metabolic stress conditions to which they are typically exposed and stabilize their adaptive metabolic reprogramming." (PMID 35495117, 2022). "Thus, identifying a suitable tyrosine kinase inhibitor (TKI) with multiple functions in modulating the EGFR, KRAS, and mTOR pathways is important to reprogram tumor metabolism and reverse mitochondrial dysfunction." (PMID 36145507, 2022). "Through EIF4A3-mediated E2F transcription factor 1 (E2F1) upregulation, the lncRNA cancer susceptibility candidate 11 (CASC11) inhibited NF-κB and PI3K/AKT/mTOR pathway activation to mediate PD-L1 expression and encourage tumor progression in a mouse model of HCC with lung metastasis." (PMID 35907881, 2022).
tumor (continued). "Notably, we found some tumor-related pathways were activated in high-risk patients, such as epithelial-mesenchymal transition, mTORC1, and PI3K/Akt/mTOR pathways (TCGA)." (PMID 36387251, 2022). "In addition, we found that higher levels of pathway activity—indicated by the expression of phosphorylated (p)-mTOR, p-AKT, and p-S6K1—were associated with lower tumor grade, smaller tumors, earlier stage at diagnosis, and luminal subtype." (PMID 35608730, 2022). "Furthermore, Myrtucommulone A was found to significantly down-regulate Akt/mTOR/autophagy signaling pathway proteins in tumor microenvironment mimicking the condition of nutrient deprivation." (PMID 36235333, 2022). "One of the ways hyperactivation of the PI3K/AKT/mTOR pathway is achieved in various tumor types is by the ROS‐mediated oxidation of key cysteine residues in negative regulators (phosphatase and tensin homolog (PTEN) and protein tyrosine phosphatase 1b (PTP1b)), which renders both proteins inactive." (PMID 35666002, 2022). "In addition, other studies have found that lncRNAs can regulate PI3K/AKT/mTOR signalling through targeted adsorption of miRNAs, thereby affecting the growth and proliferation of a variety of tumour cells, including pharyngeal squamous cell carcinoma cells." (PMID 35883139, 2022). "In both tumor entities, monotherapy with mTOR inhibitors has modest, if at all any activity." (PMID 35814409, 2022). "Overall, our findings suggest that the miR-199a/Rheb/mTOR axis may function as a tumor suppressor within this regulation network." (PMID 35844793, 2022). "Besides, C2orf40 inhibited the phosphorylation levels of PI3K, AKT, mTOR, and cell cycle-related proteins in tumor cells." (PMID 35676661, 2022). "IL-7R, mTOR and tumor stage were the strongest predictors of survival." (PMID 35778432, 2022). "Thus, the expression of PI3K, AKT, mTOR and their phosphorylation level was determined in our study in order to investigate the role of PI3K/AKT/mTOR pathway in the anti-tumor effect of ASF1b-si." (PMID 35399734, 2022). "The third solution is combining mTOR inhibitors with other anti-tumor therapies." (PMID 36497433, 2022). "ONC201 inhibited OC cell proliferation and tumor growth, which was associated with changes in expression of a constellation of proteins involved in apoptosis, cell cyclin, oxidative stress, angiogenesis, invasion, AMPK/mTOR and MAPK pathways." (PMID 35372029, 2022). "The tumor tissues were analyzed for the activation status of mTOR-AMPK-Akt signaling." (PMID 35211405, 2022). "Furthermore, inhibition of the PI3K/Akt/mTOR signaling pathway had been found to enhance radiosensitivity of tumor cells." (PMID 35571014, 2022). "PI3K/AKT/mTOR is an intracellular signaling pathway that plays a key role in tumor development." (PMID 35477364, 2022). "It was speculated by some researchers that the MOR could affect various aspects such as angiogenesis and immune regulation by activating signal pathways of PI3K, Akt, and mTOR, and promote tumor recurrence and metastasis." (PMID 35966857, 2022). "Importantly, 8GL alone or in combination with an mTOR inhibitor remarkably impaired tumor growth and extended mouse survival in an AML xenograft model accompanied by enhanced cell differentiation." (PMID 36437247, 2022). "However, after inhibiting miR-18a-5 in EVs, miR-18a-5p was lowered, levels of NACC1 mRNA, p-AKT and p-mTOR were elevated, the ability of EVs to inhibit tumor growth was obviously weakened, the number of lung metastatic nodules was raised (all P < 0.01)." (PMID 35672774, 2022). "Notably, both analyses showed that the PI3K/AKT/mTOR signaling pathway were significantly enriched in tumor-related pathways, and the activation of this pathway was negatively correlated with CAMK1D expression." (PMID 35494053, 2022). "The dual PI3K/mTOR inhibitor PI-103 is available to treat various tumor types." (PMID 35918352, 2022).
tumor (continued). "The knockout of these genes or the inhibition of mTOR signaling activity were sufficient to enhance memory-like CD4+ T cell responses and to provide prolonged help to CD8+ T cells to achieve target tumor cell killing, underscoring a central role for mTOR signaling in this context." (PMID 35990699, 2022). "In addition, it has been reported that tumor-associated macrophages (TAMs) can up-regulate the expression of REDD1, a negative regulator of mTOR, under hypoxic conditions." (PMID 35681715, 2022). "Therefore, further studies are warranted to elucidate the role of PI3K/AKT/mTOR signalling networks on immune regulation and tumour progression in OCCC." (PMID 35043008, 2022). "Knockdown of KLF4 prevents mTOR/Rictor interaction and tumor metastasis of NSCLC in vivo." (PMID 35982899, 2022). "Our study results displayed that since LAGE3 might promote tumor development in HCC via PI3K/AKT/mTOR and Ras/RAF/MAPK pathways, the development of LAGE3 target drugs may be a new treatment strategy for HCC patients." (PMID 35313850, 2022). "Both mTOR inhibitors, rapamycin and Ku-0063794, were effective at reducing tumor diameters." (PMID 36551683, 2022). "The activation of the AMPK-pathway may reduce the activity of insulin in promoting tumor progression and can inhibit the mammalian target of rapamycin (mTOR), which is closely connected to tumor cell proliferation." (PMID 36280839, 2022). "It has been reported that inhibition of PI3K/AKT/mTOR pathway induced HRD in the tumor cells." (PMID 35419627, 2022). "Thus, we suggested that LINC00674 activated the mTOR signaling pathway and facilitated tumor progression by enhancing NOX1 expression in HCC cells." (PMID 36118523, 2022). "Moreover, insulin also promotes tumor cell growth by altering the energy metabolism of tumor cells through the aberrant mTOR pathway to upregulate glucose uptake and glycogenolysis." (PMID 35933633, 2022). "The metabolic changes that PI3K/AKT/mTOR induce promote tumor growth." (PMID 35053485, 2022). "Spatial visualization of fatty acids by imaging mass microscopy showed that C16:1 obviously accumulates in tumor tissue, and C16:1 may promote the EC cell invasion and metastasis through mTOR signaling." (PMID 36227107, 2022). "Moreover, adiponectin was deemed to be a strong inhibitor of the PI3K/Akt/mTOR pathway, thus limiting the tumor cell growth induced by insulin and by other growth factors." (PMID 35384390, 2022). "We suspect that the inhibition of the AKT/mTOR pathway may contribute to the anti-tumor effects of CPSF7." (PMID 36349192, 2022). "In addition, an upregulation of the p38 MAPK pathway was identified in the AKT/mTOR inhibitor-resistant tumor cells by kinome profiling." (PMID 35454789, 2022). "Consequently, co-targeting of NOP56 and mTOR profoundly enhances KRAS-mutant tumor cell death in vitro and in vivo." (PMID 35039048, 2022). "The HOTAIR/miR-326 axis was shown to regulate FUT6 expression to promote fucosylation of CD44 in colorectal cancer, and fucosylated CD44 could activate the PI3K/AKT/mTOR pathway to promote tumor progression." (PMID 35936713, 2022). "Curtis R Chong and colleagues proposed that the resisting to EGFR-targeted therapy in tumor cells could be relevant to the abnormally activating of PI3K/AKT/mTOR pathway." (PMID 35574327, 2022).
tumor (continued). "Spatial visualization of fatty acids showed that C16:1 and C18:1 obviously accumulate in tumor tissue, and C16:1 may promote EC cell invasion and metastasis through mTOR signaling." (PMID 36227107, 2022). "The treatment response of a RAF kinase, sorafenib, could be enhanced by the administration of mTOR inhibitors in a hepatoma carcinoma cell tumor xenograft model." (PMID 36539659, 2022). "Clustering analysis of BMDCs and MDSC-DCs in the genes of mTOR signaling pathway found that tumor suppressor factors such as Pten, Tsc1, Ddit4, mtor, Rptor, and other genes involved in controlling the activity of rapamycin complex 1 (mTORC1) were found in MDSCs-DCs and are all down-regulated." (PMID 36567953, 2022). "Moreover, a previous review has demonstrated that activation of the PI3K/AKT/mTOR pathway in tumor cells can increase levels of VEGF, nitric oxide, and angiopoietins to regulate angiogenesis." (PMID 34164393, 2021). "Third, we determined that the PRMT4-related tumor-promoting effect in HCC may depend on the activation of the AKT/mTOR pathway." (PMID 34522186, 2021). "In addition, mTOR is considered to be an important pathway to promote tumor growth, and dysregulated expression of mTOR can promote tumor proliferation and metabolism." (PMID 34512796, 2021). "Furthermore, changes in the IGF-1 R/PI3K/AKT/mTOR axis were assessed in ropivacaine-challenged cells and tumor xenograft animals." (PMID 34696683, 2021). "The PI3K/Akt/mTOR pathway is important in tumor development and metastasis." (PMID 34831139, 2021). "Since the contribution of mTOR signaling to tumorigenesis has been revealed in many tumor studies, targeting mTOR as a radiosensitizing strategy may be a reasonable approach." (PMID 33959512, 2021). "Indeed, preclinical studies have demonstrated AMPK1 induction to suppress glycolysis through mTOR signalling, which was able to decrease tumour burden in DMG orthografts." (PMID 34944870, 2021). "However, inhibitors targeting the PI3K/AKT/mTOR signaling pathway reportedly restore sensitivity to inhibit tumor growth under a combination treatment." (PMID 33471836, 2021). "In addition, the mTOR signaling pathway can also affect the protein’s translation, synthesis, apoptosis, and the occurrence and proliferation of tumor cells by regulating ribosome synthesis and downstream gene transcription." (PMID 33897438, 2021). "Patients in the pathCR group had significantly higher tumour mutational burden and neoantigen load, frequent copy number alterations but fewer structural variants and enrichment for driver mutations in the PI3K/AKT/mTOR signalling pathway." (PMID 34256782, 2021). "Therefore, we expect that the subtype-1 are possibly more responsive to drugs that target the mTOR than will the subtype-2 tumours." (PMID 34506537, 2021). "In addition, mTOR served as a downstream target of PI3K/AKT pathway also can be activated to involve with tumor cell progression and chemoresistance." (PMID 34417976, 2021). "It is worth investigating why autophagy caused by mTOR makes the tumor more sensitive, but autophagy induced by TFEB does not show this." (PMID 34830772, 2021). "In HCC cells, AKT/mTOR/S6 are involved in lipogenesis and tumor growth." (PMID 33477262, 2021). "Many drugs that were tested in clinical trials, such as MEK1 and mTOR inhibitors, may be useful for the treatment of neurofibroma because they affect tumor vasculature." (PMID 34359780, 2021). "On this basis, it was suggested that inactivation of hnRNPM or reversion of disease-relevant splicing events regulated by this RBP could be exploited to increase the efficacy of inhibitors of the PI3K/AKT/mTOR pathway in this tumor type." (PMID 34680108, 2021).
tumor (continued). "It has been proposed that rapamycin induces apoptosis of OS cells and that treating OS by targeting the mTOR pathway alone could inhibit proliferation and promotion of these tumor cells." (PMID 33467481, 2021). "PI3K/AKT/mTOR pathway is involved in the sensitivity of tumor cells toward cisplatin." (PMID 37303943, 2021). "In addition, PI3K-Akt-mTOR also plays a crucial role in tumor growth, just as it is a major signaling pathway involved in tumorigenesis and development." (PMID 34521930, 2021). "Furthermore, the suppression of AKT/mTOR/p70S6K signaling is reported to attenuate endothelial cell proliferation, which is critical for controlling the tumor microenvironment and angiogenesis." (PMID 34279440, 2021). "mTOR is reported to regulate tumor growth, survival, metabolism, and immunity." (PMID 34916492, 2021). "The p-Akt and p-mTOR of xenograft tumor were determined by western blot." (PMID 34895234, 2021). "Similarly, the targeted delivery of miR-99b in HCC or subcutaneous Lewis lung cancer mice re-educated TAMs from M2 to M1 phenotype by targeting κB-Ras2 and/or mTOR, thereby enhancing immune surveillance and impeded tumor growth." (PMID 33672261, 2021). "Moreover, treatment with ASP also reduced the H-Score of phosphorylated S6 in the HFD and LFD groups compared with the control mice, indicating that ASP inhibited tumor growth through the AMPK/mTOR pathway in vitro and in vivo." (PMID 34336674, 2021). "In the current study, we compared the expression level of mTOR and p-mTOR between ccRCC and adjacent kidney tissues, evaluated its prognostic significance using TMA, then revealed the tumor-immune interaction of mTOR in ccRCC using online databases (TIMER and TISIDB) and HE staining." (PMID 34458019, 2021). "The AMPK/mTOR signaling pathway exhibited a strong correlation with tumor growth and proliferation." (PMID 33231372, 2021). "mTOR hyperactivity has multifunctional tumor growth–promoting effects." (PMID 35029792, 2021). "Additionally, AMPK phosphorylation was obviously induced, and the tumor mTOR pathway was suppressed." (PMID 34098990, 2021). "Moreover, the activity of mTOR in tumor was promoted by BO treatment as indicated by the phosphorylation of 4E-binding protein 1 (4E-BP1) and ribosomal protein S6, and hyper-autophagy was consequently restrained." (PMID 34658867, 2021). "In several cancer cells, the expression, and the activity of ERRα, and its cofactor PGC-1, is further influenced by oncogenic signals (e.g., IGF1 receptor pathway, estrogen signaling, mTOR pathway) and induces metabolic programs favoring cell growth and tumor progression." (PMID 33718197, 2021). "In contrast to glutamine, the increased intercellular concentration of L-Arginine directly enhances remarkable metabolic reprogramming and survival capacity of CD4+ and CD8+ T cells, independently of mTOR signaling or downstream metabolites, thus, improves anti-tumor activity." (PMID 35250965, 2021). "Additionally, MYC is involved in glucose/glutamine sensing and mTOR-dependent Akt functions, which regulate the bioenergetic balance of tumor cell growth and survival." (PMID 35029792, 2021). "Several clinical trials of renal carcinoma, glioma, neuroendocrine and gastrointestinal cancers are ongoing, involving mTOR inhibitors in combination with anti-angiogenic treatments, however, the results may vary between tumor types." (PMID 34257622, 2021). "In up to 40% of BCs, mTOR signaling is activated and related to tumor progression." (PMID 34716292, 2021). "Moreover, activated AMPK can inhibit mTOR, and then induce tumor cell apoptosis, cell-cycle arrest, and autophagy, thereby directly conferring an antitumor effect." (PMID 34149406, 2021).